CD68 (CD68 molecule)
Diseases named in the same sentence as CD68 in open-access papers (continued):
Sharing a sentence is not in itself a finding about the gene and the disease.
melanoma (continued). "To explore the immune context more broadly we developed a pan-immune OPAL panel comprising CD3 (T cells), CD20 (B cells), CD68 (macrophages), CD11c (likely dendritic cells), SOX10 (melanoma) and DAPI (cell nucleus)." (PMID 30042403, 2018). "This may be MAPK-driven, as increasing accumulation of CD68+ and CD163+ microglia is similarly observed in melanoma, correlating with greater tumour size and Breslow depth, and at significantly higher levels in BRAF-altered samples." (PMID 39948623, 2025). "Despite the lack of change in TNF-α levels, we can conclude that melanoma inhibits M1 polarization based on the CD68 expression results." (PMID 39995996, 2025). "In the absence of melanoma specific markers, there was substantial risk of misinterpretation as a histiocytic neoplasm as BCL-1, CD68, S100, and, rarely, BRAF expression is potentially supportive of RDD, while BRAF and CD68 are frequently seen in EC." (PMID 40658291, 2025). "Spatial transcriptomic data from Spatial DB further confirmed that PSME2 expression patterns overlapped substantially with those of the macrophage marker CD68 and the M1 macrophage marker TLR2 in BRCA and melanoma, implied potential co-localization of these genes." (PMID 38385075, 2024). "Confirming these findings in a clinical setting, we identified high CD68 expression in malignant melanoma as a negative predictor for monotherapy with PD-1 inhibitors." (PMID 36980787, 2023). "When analyzing the malignant melanoma group, shorter median progression-free survival (PFS) was found in tumors positive for nuclear FoxP3 in tumor-infiltrating lymphocytes (TILs) (p = 0.048, HR 3.04) and for CD68 expression (p = 0.034, HR 3.2)." (PMID 36980787, 2023). "CD8+ CTLs associated positively with PD-L1+ tumor and stromal immune cells (p-values 0.015 and <0.001, respectively), IDO+ melanoma cells (p < 0.001) and tumor nest CD68+ macrophages (p = 0.016) (data not shown)." (PMID 36551965, 2022). "We demonstrated reproducible staining with the accurate detection of immune cell markers CD8, CD68, CD16, immune checkpoint PD-L, and melanoma tumour marker SOX10 in a multiplex methodology compared with chromogenic immunohistochemistry and single-plex immunofluorescence staining for all markers." (PMID 35664673, 2022). "Fluorescent IHC and spectral microscopy have the advantage of multiple marker detection; accordingly, it was used to analyze immune infiltrates in primary melanomas, showing that combination assessment of CD8+ lymphocytes/CD68+ macrophages ratio in the stroma correlated with shortened survival." (PMID 34439098, 2021). "Staining is positive for CD68 and vimentin and negative for Melan-A, human melanoma black (HMB)-45, S100 protein, pan-cytokeratin (CK), and actin." (PMID 34449582, 2021). "For image quantification, we chose CD68 for macrophage segmentation because very few CD68+ cells were negative for CD115 or CD163, indicating that very few cells other than macrophages were CD68+ in melanoma tissues." (PMID 34439098, 2021). "In metastases from melanoma patients, high levels of miR-146a, miR-155, miR-125b, miR-100, let7e, miR-125a, miR-146b, and miR-99b were detected and correlated with CD163, CD14, CD209, CD68, ITGAM, and CD33 myeloid markers." (PMID 32793228, 2020). "On a small cohort of melanoma patients treated with anti-PD-1, non-responders displayed a significantly higher proximity of CD68+ myeloid cells to CD8+ T cells compared to responders in pre-treatment and on-treatment biopsies." (PMID 32793228, 2020). "In many melanomas, there were no CD68+ macrophages within tumours or peritumoural tissue, but there were high levels of CD163+ macrophages across almost all cases." (PMID 32843682, 2020).
melanoma (continued). "Intra-assay reproducibility and quantification was accomplished by manually staining 5 serial sections from three different tissue types (tonsil, melanoma, NSCLC) with one set for each of the UltiMapper PD-1 (CD3, CD45RO, PD-1, CK/Sox10) and PD-L1 (CD8, CD68, PD-L1, CK/Sox10) I/O kits." (PMID 30400835, 2018). "Moreover, by analyzing melanoma samples for SMA and both CD163 and CD68 expression using immunohistochemistry, we observed fibroblasts and macrophages localized together in bands of connective tissue traversing melanoma metastases taken from skin and lung." (PMID 28450382, 2017). "Moreover, melanomas can express other markers such as CD31, CD68, epithelial membrane antigen, and CAM5.2." (PMID 27998306, 2016). "It is important to mention that, since melanoma cells can lose MART1 expression, especially on the periphery of the tumor, cell morphology and the expression patterns of CD68 or SMA were all taken into account during the process of peritumoral cell identification." (PMID 27338362, 2016). "Diagnostic confirmation requires histopathological correlation through immunohistochemistry, demonstrating the absence of melanocytes and the presence of dermal CD68+ melanin-laden macrophages, resulting from the phagocytosis of melanin released during melanoma cell degradation." (PMID 41552050, 2025). "Cells that co-stained with CD68 and GPNMB were scattered in the compound nevi, whereas in the in situ and vertical melanomas and lymph-metastasized melanoma, these co-stained cells were located internal to the melanoma cells or within the tumor microenvironment (B and EV1A)." (PMID 38719996, 2024). "Furthermore, in human melanoma tissues, the immunohistochemical expression of macrophage marker CD68 on tumor cells is a well-known phenomena which was not analyzed at genetic or protein levels." (PMID 36754910, 2023). "Interestingly, we identified that in the primary cases with focal ASS1 expression (5%–30%) the majority of cells with the highest expression were in fact CD68‐positive macrophages (or melanophages) and not melanoma cells." (PMID 35466524, 2022). "Controversially, in melanoma, CD68+ TAMs characterized by M1 phenotype, however, not statistically significant correlations were found for the total amount of CD68+TAMs and clinical parameters of melanoma progression in patients." (PMID 36686729, 2022). "The tumor cells were positive for CD68, S100, CD4 and lymphocyte common antigen, while epithelial membrane antigen, HMB-45, CK AE1/AE3, myogenin, desmin, CD1a, CD21 and SALL-4 were negative thus ruling out rhabdomyosarcoma, extrarenal rhabdoid tumor, Langerhans cell sarcoma and malignant melanoma." (PMID 31890359, 2019). "Moreover, by combining two negative biomarkers, FoxP3 (Tregs) and CD68 (TAMs), we can select an even more specific group of patients who benefited from treatment with PD-1 inhibitors the most, and in the melanoma subgroup, we confirmed its predictive value but not prognostic." (PMID 36980787, 2023). "Thus, it is clear that CD68 is not a pan-macrophage marker in melanoma." (PMID 32843682, 2020). "In the melanoma tissue itself, 50% of dendritic cells, 35% of CD45 positive cells, 40% of CD11b positive cells, and no CD68 positive cells were found." (PMID 33921688, 2021). "In the melanoma tissue itself, 5% of dendritic cells, 20% of CD45 positive cells, 10% of CD11b positive cells, and no CD68 positive cells were found." (PMID 33921688, 2021). "In the melanoma tissue itself, 65% of dendritic cells, no CD45 positive cells, 5% of CD11b positive cells, and no CD68 positive cells were found (for a summary of the results)." (PMID 33921688, 2021). "A dense intratumoral infiltration of both CD68+ve and CD163+ve TAMs has been reported in deeply-invasive malignant and metastatic melanomas compared to non-metastatic melanomas, and in malignant compared to benign melanocytic lesions." (PMID 34831352, 2021).
melanoma (continued). "In the melanoma tissue itself, 5% of dendritic cells, 35% of CD45 positive cells, 5% of CD11b positive cells, and no CD68 positive cells were found." (PMID 33921688, 2021). "Subsequently, other large-scale studies did not corroborate the correlation between CD68 positive TAM number and melanoma survival." (PMID 34439098, 2021). "Cluster differentiation 68 (CD68) and CD163 were positive and S100, CD1a, langerin, human melanoma black 45 (HMB-45) and Melan-A were negative in immunohistochemical staining." (PMID 32532290, 2020). "After three passages, the cells isolated from the melanomas by collagenase digestion consisted almost entirely of spindle-shaped, fibroblastic mononuclear cells, which did not stain for CD14, CD68, VNR, TRAP, HMB-45 and S100." (PMID 16641914, 2006). "Both CD68+ve and CD163+ve TAMs were more abundant in metastatic compared to non-metastatic melanomas, and in malignant compared to benign melanocytic lesions, a finding which has been associated with tumor progression and metastasis aas well as poor clinical outcome." (PMID 34831352, 2021). "Malignant melanoma, GIST, MPNST, sarcomatoid renal cell carcinoma, and malignant fibrous histiocytoma will be positive for vHMB-45, c-kit, S-100, RCC marker, and CD68, respectively, and will be negative for desmin, synaptophysin, inhibin, Melan-A, and calretinin." (PMID 25685588, 2015). "While CD68+ macrophages may favor melanoma cells invasion, DC accumulation and activation of CTL were present in SLN+ of melanoma patients with no other positive correlation in the downstream LNs." (PMID 26218530, 2015). "We found that melanoma induction and combination ICI treatment to non-cancer and cancer-bearing mice led to a significant increase in microglial activation, as shown by elevated hippocampal dual-immunoreactivity for the CD68 and IBA1 at two months post-combination ICI treatments." (PMID 40313772, 2025). "There was negative correlation between CD68 and CD163 mean fluorescence intensity (MFI) (R= −0.36, n = 6, p < 0.001); however, neither CD163 nor CD68 nor CD115 defined separated M1/M2 macrophage subsets, indicating that they are pan-macrophage markers in melanoma." (PMID 34439098, 2021).
Obesity (90 papers, 2010 to 2026). Accumulation of substantial excess body fat. "In particular, LAMs are recruited from the circulation to the adipose tissue based on their expression of CD68 to prevent adipocyte hypertrophy and loss of systemic lipid homeostasis in obesity." (PMID 37182562, 2023). "As obesity is associated with adipose tissue inflammation, mRNA levels of genes involved in macrophage infiltration (Cd68 and F4/80) and proinflammatory action (Tnfα) were also evaluated in perigonadal fat tissue." (PMID 36353242, 2022). "The expression of inflammatory markers as CD68, IL-6, TNFα and lysozyme is increased during obesity and associated with insulin resistance." (PMID 36432612, 2022). "The presence of hCLS-B and of CD68 + CLS-B were associated with obesity; CD68 + CLS-B were associated with insulin resistance and adverse prognosis." (PMID 34294716, 2021). "The observed association with insulin resistance would suggest that the obesity-associated CD68 + CLS-B we identified in our patients contained classically activated, pro-inflammatory M1 macrophages (reflected by the metabolic associations)." (PMID 34294716, 2021). "HFD-induced obesity was associated with increased expression of inflammatory markers CD68 and F4/80 (CH vs. CC, P < 0.05, HH vs. CC, P < 0.01, CH-STZ vs. CC, P < 0.01, HH-STZ vs. CC, P < 0.001)." (PMID 28225809, 2017). "Because inflammation is an established hallmark of obesity, we examined gene expression of the macrophage markers CD68 and F4/80 by PCR in the adipose tissue." (PMID 28612048, 2017). "In conclusion, a decreased MCR1/CD68 ratio (mainly in visceral adipose tissue) is a potential marker of obesity-associated adipose tissue dysfunction, and linked to decreased expression of mitochondrial genes in the muscle." (PMID 23951013, 2013). "In fact, the associations of CD68 gene expression with fasting glucose, leptin and adipogenic gene expression were closely dependent on obesity." (PMID 23951013, 2013). "The most significant associations of both MCR1/CD68 and CD68 levels with obesity in the cross-sectional study were mainly found in visceral adipose tissue." (PMID 23951013, 2013). "Our data demonstrate that obesity is linked to increased adipose tissue expressions of CD68 and TNF-α, and that both, CD68 and TNF-α expressions predict insulin sensitivity independently of known confounders." (PMID 21197447, 2010). "Here, we confirmed an increased CD68 gene expression in association with obesity." (PMID 23951013, 2013). "Notably, therapeutic propagermanium administration did not result in decreased expression of total macrophage marker (CD68) or increased M2 macrophage marker expression, indicating that decreasing pro-inflammatory M1 macrophage content is sufficient to improve obesity-associated insulin resistance." (PMID 28076416, 2017). "Given the well‐established links among adipocyte size, cell death, and inflammation, we quantified CD68‐positive macrophages, the predominant inflammatory cells in adipose tissue of individuals with obesity." (PMID 40077894, 2025). "CD68 immunoreactive macrophages were more abundant in affected areas (p = 0.005), and their number was similar to that found in fat from patients with obesity (p = 0.17)." (PMID 40077894, 2025). "Previously, a positive association between the immunohistochemical expression of GSHR and CD68-macrophage infiltration was shown in the epicardial adipose tissue of patients with obesity undergoing coronary artery bypass graft surgery." (PMID 38999303, 2024). "An upregulation of TLR4 (P < 0.05), CD68 (P < 0.05), SPP1 (P < 0.05) and CCL2 (P < 0.05) together with a downregulation (P < 0.05) of ADIPOQ levels in the jejunum from patients with obesity-associated T2D were found." (PMID 38315242, 2024). "The increase in CD68-positive microglia suggests that HFD-induced obesity promotes microglia phagocytic activity." (PMID 37457817, 2023).
Obesity (continued). "For CD68, significant effects of obesity (F = 139.5; p < 0.0001) and OEA-DS application (F = 43.47; p < 0.0001), and a significant interaction effect of these factors (F = 38.46; p < 0.0001) were found in both the white and red pulp." (PMID 37892420, 2023). "Nonetheless, the majority of liver myeloid cells (HLA-DR+CD68+) in both lean individuals and individuals with obesity were localized to the zones between the portal tracts and central veins, irrespective of their phenotype (resident or recruited)." (PMID 37414931, 2023). "Our clinical results demonstrate that patients with obesity have increased levels of STING in human CD68+ lung macrophages compared to control individuals." (PMID 36782056, 2023). "We observed that the lung sections collected from patients with obesity showed increased numbers of dual STING+/CD68+ macrophages in lung tissues compared to control individuals." (PMID 36782056, 2023). "Both the marker for total macrophage infiltration (CD68) and its pro-inflammatory counterpart (CD11c) showed similar trends with both being most highly expressed in women with obesity-diabetes and significantly least expressed in lean populations." (PMID 35933445, 2022). "Monocytes and macrophages appear to be associated with adiposity in patients with obesity and COVID‐19, with CD14+CXCR6+ cells positively correlated with the elevated BMI and CD68+ cells in the epicardial adipose tissue." (PMID 35837843, 2022). "Age seems to have an effect on microglial activation in obesity in the striatum, as increased microglial activation and the phagocytic capacity marker CD68+ were observed in aged obese mice." (PMID 33808700, 2021). "Our findings are consistent with the prevailing model, that the presence of CD68 + CLS-B represents a phenotype linking obesity, macrophage-mediated inflammation and breast cancer." (PMID 34294716, 2021). "Aging and obesity seem to exert a synergistic effect on microglial activation in the hippocampus, as indicated by the exacerbated microglial activation (CD68+) and enrichment of microglial proinflammatory genes, compared to aged or DIO groups alone." (PMID 33808700, 2021). "Compared to the normal control, obesity and gastrectomy resulted in significantly higher CD68, EMR-1, and MCP-1 gene expressions." (PMID 33086562, 2020). "Obesity induced a significant increase in CD68-positive cells in both saline and MCT treated female Zucker rats compared to the lean groups." (PMID 32493503, 2020). "Maternal overnutrition in a sheep model of obesity demonstrated that inflammatory markers such as CD-68, TGF-β1, and TNF-α found in the mother are also identified in the offspring after birth." (PMID 30027100, 2018). "Obesity and T2DM were associated with increased CD68 marker expression (P<0.001) while CD11b and CD163 expression were significantly inhibited in T2DM (P<0.005)." (PMID 30356719, 2018). "Next, we found that the increased TLR8 gene expression in the adipose tissues in obesity/T2D paralleled with enhanced expression of monocyte/macrophage markers such as CD68, CD11c, CD86, and CD163." (PMID 27980459, 2016). "MCR1/CD68 ratio increased significantly after weight loss in parallel to adipogenic genes, such as FASN, ADIPOQ, IRS1 and SLC2A4, whereas LEP (an obesity gene marker) and IL6 (an inflammatory marker) decreased." (PMID 23951013, 2013). "This was consistent with the increase in immunoreactivity for CD68 (macrophages) in both adipose tissue depots during high fat diet-induced obesity." (PMID 22276186, 2012). "In summary, the present study demonstrated relationships between obesity, adipose tissue inflammation reflected by increased adipose tissue expressions of CD68 and TNF-α, and insulin resistance in patients with COPD." (PMID 21197447, 2010).